SMARCA4 (SWI/SNF related BAF chromatin remodeling complex subunit ATPase 4)
Diseases named in the same sentence as SMARCA4 in open-access papers (continued):
Sharing a sentence is not in itself a finding about the gene and the disease.
cancer (continued). "A wide variety of benign and malignant tumors with alterations in several genes belonging to the SWI/SNF complex have been described, including SMARCB1, SMARCA4, SMARCA2, and ARID1A." (PMID 39590317, 2024). "Identifying a number of putative drivers, ARID1A, CHD4, HCFC1, STAG2, SMARCA4, and NCOR1 are known cancer driver genes." (PMID 37444571, 2023). "Our results also showed that overexpression of SMARCA4 significantly decreased E-cadherin expression, but upregulated vimentin levels in OSCC cancer cell lines." (PMID 36902184, 2023). "ARID1A is mutated in 9% of all cancers based on a survey of 24 whole exome studies across 18 different cancer types, followed by PBRM1 (4%) and SMARCA4 (3%)." (PMID 38275587, 2023). "SMARCA4 (BRG1) and SMARCA2 (BRM) are the two paralogous ATPases of the SWI/SNF chromatin remodeling complexes frequently inactivated in cancers." (PMID 37210563, 2023). "TCGA database was used to analyze the expression of NOTCH3 and SMARCA4 in the CRC tissues and the adjacent normal tissues, and the results revealed that both of them showed higher expression in cancer tissues when compared to the adjacent tissues." (PMID 35900231, 2022). "ACBI1 induced selective, fast and complete degradation of the engaged targets SMARCA2, SMARCA4 and PBRM1 in MV-4-11 cancer cells with DC50 of 6 nM and 11 nM for SMARCA2/4, respectively." (PMID 35983982, 2022). "While bromodomain inhibition was not as effective as ATPase inhibition at curbing growth of some SWI/SNF mutant cancers, PFI-3, a small molecule selective for the SMARCA4/SMARCA2/PBRM1 bromodomains, sensitized cancer cells to DNA-damaging agents." (PMID 35323214, 2022). "The mutational rates and variation types of six SWI/SNF complex genes (ARID1A, ARID1B, ARID2, SMARCA4, SMARCB1, and PBRM1) were analyzed retrospectively by integrating next-generation sequencing data of 4591 cases covering 18 cancer types." (PMID 36371186, 2022). "We found that SMARCA4 expression is highly related to five MMR genes and to MSI in most cancer types." (PMID 34675941, 2021). "The role of SMARCA4, an ATPase subunit of the SWI/SNF chromatin remodeling complex, in genomic organization is well studied in various cancer types." (PMID 34771636, 2021). "We note that CDH1 mRNA expression is maintained in SMARCA4 depleted cells, yet the protein is mislocalized and rapidly depleted in response to RSV infection, consistent with other studies in cancer." (PMID 33732255, 2021). "Specifically, ACTL6A, SMARCD1, SMARCA4 and BRD9 are among the top upregulated genes in cancers compared with the paired control samples." (PMID 34598711, 2021). "SMARCA4 and SMARCA2 are mutually exclusive catalytic subunits of the SWI/SNF complex, and the inhibition of SMARCA2 activity appears to be synthetic lethal in cancer cells carrying SMARCA4-inactivating mutations, an effect that could be explained by paralogue insufficiency." (PMID 34262032, 2021). "These genes include known and novel FOXL2 targets (TGFB2, SMARCA4, HSPG2, MKI67, NFKBIA) and are enriched for neoplastic pathways (Proteoglycans in Cancer, Chromatin remodeling, Apoptosis, Tissue Morphogenesis, Tyrosine Kinase Receptors)." (PMID 33639972, 2021). "Important cancer-related molecules were observed as potential regulators for the DEPs, such as MYC, CD3, CEBPB, PI3K complex, SMARCA4 and the anti-cancer chemical drugs 5-fluorouracil, dexamethasone, sirolimus (rapamycin) and tretinoin." (PMID 33656060, 2021).
cancer (continued). "Among the genes listed in the COSMIC50 database for cancer, seven blood lifespan cis-eGenes (ALDH2, BCL3, CDKN2A, FES, HIST1H3B, SH2B3, and SMARCA4) were identified (fold enrichment = 1.4, P = 0.22, hypergeometric test)." (PMID 32358504, 2020). "However, the role of SMARCA4 in cancer occurrence and progression remains unclear." (PMID 32162380, 2020). "CLCLs were found to occur even in key cancer genes, such as the STK11, NF1, SMARCA4, and PTEN genes." (PMID 32887687, 2020). "We found that these CLCLs exist even in pivotal cancer-related genes, such as the STK11, NF1, SMARCA4, and PTEN genes." (PMID 32887687, 2020). "Among the CASEs, 26 events were identified to generate new isoforms in 22 cancer drivers, such as KRAS, SMARCA4 and FBXW7." (PMID 31695792, 2019). "These examples depict a striking exemption of the concept of hard-wired SMARCA2/SMARCA4 paralog dependency and constitute a potential mechanism for resistance to BAF targeted cancer therapies." (PMID 31406271, 2019). "Here, we performed a computational meta-analysis using gene expression, prognosis, and clinicopathological data to clarify the role of SMARCA4 and the alternative SWI/SNF ATPase SMARCA2 (BRM) in cancer." (PMID 29391527, 2018). "In order to clarify this complex scenario, we have now used data from The Cancer Genome Atlas (TCGA) and other databases to investigate the levels of SMARCA4 and SMARCA2 mRNAs in several types of cancer." (PMID 29391527, 2018). "Thus vulnerability to AURKA inhibitors might not be limited to the loss of SMARCA4 in NSCLCs but might occur in other cancers with mutations in SMARCA4 or other SWI/SNF components that cause a loss of SWI/SNF function." (PMID 28102363, 2017). "Several cancer-related genes such as STK11, SMARCA4, and RUNX1 were located within the HMA-resistance-specific CNAs." (PMID 28052028, 2017). "The well-documented cancer-related genes NOTCH1, CDKN1A, EGR1, AKT3, TNF, MMP9, and SMARCA4 are located in the center of this newly constructed subnetwork." (PMID 28500316, 2017). "Strikingly, all of the chromatin remodeling factors (SMARCA1, SMARCA2, SMARCA4 and SMARCA5) are shown to be differentially expressed in diverse cancer cell types." (PMID 26030138, 2015). "Although SMARCA4 and SMARCA2 display high homology and presumably have overlapping functions, other observations suggest that they have different roles in cancer." (PMID 25391308, 2014). "The mutations in the genes that have regulatory roles in gene expression have been reported in lung and other cancers, such as chromatin remodeling factors (e.g. ARID1A/BAF250A and SMARCA4/BRG1) and splicing factors (e.g. U2AF1 and RBM10)." (PMID 25378332, 2014). "Therefore, SMARCA4 protein expression is more likely to be defective in NSCLC and CUP cells compared to other cancers." (PMID 40866717, 2025). "In contrast to the non-degrader form of ACBI1, which had no anti-cancer effect, the ACBI1 PROTAC killed SMARCA4-dependent leukemia cells as well as SWI/SNF-deficient cancer cells that are dependent on residual SWI/SNF activity." (PMID 38390898, 2024). "SMARCA4 and SMARCA2 are two important genes in the field of cancer genetics." (PMID 38656564, 2024). "The carcinomas were then evaluated immunohistochemically for SMARCB1 and SMARCA4 proteins." (PMID 39590317, 2024). "Twelve cancers had a high posterior probability of SMARCA4-d despite being SMARCA4 WT and lacking pathogenic events." (PMID 36883553, 2023). "In this study, SMARCA4 negatively regulated 4-HNE accumulation in HCC, suggesting that it positively regulates the expression of 4-HNE metabolic enzymes and contributes to 4-HNE metabolism and its decrease in cancer tissues." (PMID 37626774, 2023). "The VHL-SMARCA2 PROTAC elicits enhanced growth inhibitory effects both in vitro and in vivo in SMARCA4mut cancer models relative to SMARCA4 wild-type (SMARCA4wt) models, in the absence of considerable tolerability issues." (PMID 36357397, 2022).
cancer (continued). "Using clinicopathologic data, we demonstrated that higher‐grade tumors display significant upregulation of ATAD2 and SMARCA4 expression, and downregulation of SMARCA2 expression, which further confirms a universal relation of these BrD proteins' expression with cancer stemness." (PMID 35049055, 2022). "We report AU-15330 as a novel, highly specific and VHL-dependent PROTAC degrader of SWI/SNF ATPase components (SMARCA2, SMARCA4 and PBRM1) that shows preferential cytotoxicity in enhancer-binding transcription factor-addicted cancers at low nanomolar concentrations." (PMID 34937944, 2022). "A pan-cancer study showed an opposing prognosis for SMARCA2 and SMARCA4 in several types of tumors." (PMID 36464671, 2022). "Subsequent to initial expansion, mutations in these loci as well as ARID1A and SMARCA4 may show a local selective advantage but do not expand far: The spatial structure of the Barrett's segment remains stable during surveillance even in patients who go on to cancer." (PMID 33664784, 2021). "We observed that MYC-amplified but not SMARCA4-mutant cancer cells were sensitive to these treatments." (PMID 34262032, 2021). "SMARCA4, the essential ATPase subunit of SWI/SNF chromatin remodeling complex, regulates transcription through the control of chromatin structure and is increasingly thought to play significant roles in human cancers." (PMID 34675941, 2021). "Protein kinases are exploitable vulnerabilities in SMARCA4- and ARID1A-mutant cancers." (PMID 33941852, 2021). "There is no possibility of preventing cancer development in patients with RTPS, but in case of detected SMARCB1/SMARCA4 mutations, the advice of surveillance and follow-up must be followed." (PMID 33692948, 2021). "We identified three hub genes (HDAC2, SMARCA4, and FOS) by PPI analysis that previous studies have suggested may be crucial in cancer development." (PMID 32391054, 2020). "This concept is further extended to non-ESCC cancer cell models, indicating SMARCA4 as a potential therapeutic target in tumors with low or absent expression of SMARCA2." (PMID 31406271, 2019). "However, other recent reports point to essential roles of SMARCA4 and/or SMARCA2 in cell survival and proliferation in some types of cancers, complicating our understanding of the role of these ATPases in cancer." (PMID 29391527, 2018). "Despite the fact that many of the carcinomas were well to moderate differentiated, they did not lose SMARCA4." (PMID 29976164, 2018). "In this case, cancer cells lacking SMARCA4 or ARID1A, two core components of the SWI/SNF complex, become dependent on the corresponding paralogs, SMARCA2 and ARID1B, respectively." (PMID 28430577, 2017). "To investigate whether the HMA-resistance-specific CNAs influence gene expression, we assayed the expression of 8 cancer-related genes by quantitative reverse transcription PCR (RT-qPCR) including BCL9, ARNT, ABL2, STK11, TCF3, SMARCA4, RUNX1, and U2AF1." (PMID 28052028, 2017). "Likewise, EZH2 inhibition sensitizes transcription activator BRG1 (ATP-dependent helicase SMARCA4) and EGFR mutant lung tumors to TopoII inhibitors, which suggest that combination therapy is a promising approach to this cancer." (PMID 27752293, 2016). "Chromosomal microarray analysis (CMA) (Cytoscan HD, Thermo Fisher Scientific) revealed monoallelic loss of SMARCB1, and an NGS panel (Oncomine Childhood Cancer Research Assay; Thermo Fisher Scientific) did not identify pathogenic variants in SMARCB1 or SMARCA4." (PMID 41180011, 2025).
cancer (continued). "Indeed, we found that overexpression of the newly characterized SWIFT domain attenuated the proliferation of several TF-addicted cancer cell lines to comparable degrees as treatment with FHD-286, a clinical-grade dual SMARCA4/2 ATPase inhibitor that recently was evaluated in Phase I studies." (PMID 40766474, 2025). "Thus, simultaneous suppression of CREBBP and EP300, but not that of either alone, causes synthetic lethality in SMARCA4/SMARCA2-deficient and SS18–SSX fusion cancers." (PMID 39625239, 2025). "However, there are few drugs that can inhibit SMARCA4 expression, and no drugs that target SMARCA4 exclusively in cancer." (PMID 38446332, 2024). "Additional correlation analysis between SMARCA4 and SRRM4 across the pan-cancer CCLE dataset revealed two well-defined groups: one including cell lines expressing SMARCA4 and lacking SRRM4, and another group with a strong positive correlation between these genes." (PMID 39080761, 2024). "In addition, cancer-associated mutations in SMARCA4 often lead to a lack of detectable protein expression, which makes full deletion of BRG1 a relevant model for understanding the impact on tumourigenesis." (PMID 35365638, 2022). "Finally, it seems that, among TTF-1 negative carcinomas, the proportion of rare carcinomas such as carcinomas muted for SMARCA4 would be more frequent." (PMID 35885495, 2022). "Wider use of gene panels including SMARCB1 and SMARCA4 among many other genes may reveal more carriers of a PV with no cancer phenotype." (PMID 33532948, 2021). "In addition to pan-cancer analysis, SynLeGG offers investigation of tissue-specific GDRs and recovers established relationships, including synthetic lethality for SMARCA2 with SMARCA4." (PMID 33997893, 2021). "Taken together, our first pan-cancer analysis of SMARCA4 indicated clinically significant correlation of SMARCA4 with prognosis, DNA methylation, protein phosphorylation, immune cell infiltration, and immunity markers as TMB and MSI, which help understand the role of SMARCA4 in tumorigenesis." (PMID 34675941, 2021). "Searching the Cancer Cell Line Encyclopedia (CCLE) we found significantly lower levels of expression of several histone demethylases (KDMs), including KDM6A and KDM6B, in SMARCA4def compared with MYCamp cells or with LC cells that are wild type for SMARCA4 and MYC." (PMID 34262032, 2021). "Interestingly, cell lines lacking SMARCA4 from a variety of cancers do not respond to retinoid therapy, while restoration of SMARCA4 expression restores retinoid sensitivity." (PMID 33968920, 2021). "In a recent study in NEPC using cancer cell lines, patient-derived organoid and large patient datasets, the expression of SWI/SNF complex was found to be altered in NEPC and higher expression of SMARCA4 (BRG1), an SWI/SNF subunit, correlated with disease aggressiveness." (PMID 34298815, 2021). "Characterization of SMARCA4-depleted IPMN-PDAC cells revealed the presence of repressive histone marks on the promoters of high-mobility group AT-hook 2 (Hmga2) gene, mediator of aggressive cancer phenotype, and other genes whose expression was reduced in IPMN-PDA." (PMID 31769422, 2019). "However, related genes (e.g., CDK1, CDK2, SMARCB1, SMARCA4) were excluded from the present study because they are either well-known genes in cancer or did not have significantly altered messenger RNA (mRNA) levels." (PMID 29712898, 2018). "Among them RB1 or ATM have a relatively clear rational and were reported be associated with poor prognosis in other types of cancer, but genes such as FAT2 or SMARCA4 may represent novel resistance genes." (PMID 27285986, 2016).
cancer (continued). "However, targeting SMARCA4, regardless of KRAS mutation, may prove a successful method of treating cancers." (PMID 38446332, 2024). "Importantly, our findings demonstrate that the patient-derived cancer cell lines initially used to define the SCLC-Y subtype actually represent SMARCA4-UT, NSCLC, or other SCLC mimics, and therefore are not representative models of “triple negative” or “inflamed” SCLC." (PMID 38180245, 2024). "Given that cancers of unknown primary have disparate origins, this raises the possibility that the patients with high posterior probability of SMARCA4-d may have metastasised from a cancer type or subtype with both high levels of SBS signatures 4 and 27, as well as high incidence of SMARCA4-d." (PMID 36883553, 2023). "Further analysis of the correlation between NOTCH3 and SMARCA4 proteins in the CRC tissues and adjacent tissues revealed a significant positive correlation between them in the cancer tissues, but not in the adjacent tissues." (PMID 35900231, 2022). "SMARCA4, a key SWI/SNF chromatin remodeling gene, is frequently inactivated in cancers and is not directly druggable." (PMID 34675941, 2021). "We depleted SMARCA4 in three MYCamp cells and observed a decrease in the EC50 for GSK-J4, which is further evidence that GSK-J4 is more toxic in cancer cells with a non-functional SMARCA4." (PMID 34262032, 2021). "Tumor suppressor SMARCA4 (BRG1), a key SWI/SNF chromatin remodeling gene, is frequently inactivated in cancers and is not directly druggable." (PMID 30718506, 2019). "However, restoration of SMARCA4 or SMARCA2 in SMARCA4/2-deficient cells did not consistently suppress SLC38A2 expression, suggesting that the elevated SLC38A2 levels in SMARCA4/2-deficient cancer cells may be an adaptation to suppressed glycolysis rather than a direct transcriptional regulation." (PMID 37210563, 2023). "Here, the authors show that the absence of SMARCA4/2 reduces chromatin accessibility at the CCND1 locus, leading to a subsequent reduction in cyclin D1 expression, which promotes vulnerability of these cancers to CDK4/6 inhibition." (PMID 30718506, 2019).